NF1 (neurofibromin 1)
Diseases named in the same sentence as NF1 in open-access papers (continued):
Sharing a sentence is not in itself a finding about the gene and the disease.
Fanconi anemia (4 papers, 2020 to 2025). Fanconi anemia (FA) is a hereditary DNA repair disorder characterized by progressive pancytopenia with bone marrow failure, variable congenital malformations and predisposition to develop hematological or solid tumors. "Growth hormone deficiency, often seen in NF1 and Fanconi anemia (FA), results in short stature and other related complications." (PMID 39641826, 2025). "Similarly, inherited disorders such as Fanconi anemia and neurofibromatosis type 1 (NF1), mediated by specific pathogenic germline mutations in genes including those within the BRCA pathway or NF1, independently and substantially elevate the risk of developing specific AML or ALL subtypes." (PMID 40892748, 2025). "Other defects in homologous recombination repair genes, such as EMSY, RAD51, ATM, ATR, Fanconi anemia, BARD1, BRIP1, PALB2, RB1, NF1, CDKN2A, and the suppression of BRCA1 transcriptional activation through gene methylation, are associated with homologous recombination deficiency (HRD)." (PMID 32679669, 2020).
fibromuscular dysplasia (4 papers, 2013 to 2024). A disorder characterized by fibrous thickening of the arterial wall resulting in narrowing of the arterial lumen. "Spontaneous VVFs are associated with conditions such as NF-1, fibromuscular dysplasia, or other connective tissue diseases." (PMID 38396452, 2024). "Approximately one-third of VVF cases are spontaneous, often observed in individuals with underlying genetic disorders, such as NF-1, or connective-tissue disorders, like Ehlers–Danlos syndrome or fibromuscular dysplasia." (PMID 38396452, 2024). "We report a case of a young patient with NF1 in whom IS was caused by fibromuscular dysplasia." (PMID 37312835, 2023). "The pathophysiology of vascular changes in patients with NF-1 is poorly understood, but fibromuscular dysplasia with prominent thickening of the tunica intima has been reported as a result of smooth muscle cell proliferation." (PMID 24200148, 2013).
germ cell tumor (4 papers, 2012 to 2022). A benign or malignant, gonadal or extragonadal neoplasm that originates from germ cells. "Furthermore, serious complications associated with NF1 (e.g., germ cell tumor, brain stem glioma, and adrenal gland neuroblastoma) were also observed." (PMID 35093157, 2022). "In term of actionability, despite some positive results of MEK inhibition in NF1-related germ cell tumors, none of the five patients with NF1 mutations treated with selumetinib (a MEK inhibitor) showed an objective response in the SAFIR02 trial." (PMID 36077738, 2022).
Gorlin syndrome (4 papers, 2012 to 2025). "We report here the case of a female proband with CALS associated to Nevoid Basal Cell Carcinoma Syndrome (NBCCS) with known PTCH1 germline mutation (C.1348-2A>G) who had been misdiagnosed with NF1 in her childhood because of 5 CALS and cutaneous nodules." (PMID 23107377, 2012).
hereditary leiomyomatosis and renal cell cancer (4 papers, 2018 to 2026). Hereditary leiomyomatosis and renal cell cancer (HLRCC) is a hereditary cancer syndrome characterized by a predisposition to cutaneous and uterine leiomyomas and, in some families, to renal cell cancer. "Genetic studies indicate associations with syndromic conditions like NF1 and Reed syndrome, emphasizing the need for vigilant surveillance and potential molecular-targeted therapies." (PMID 42093923, 2026).
histiocytic sarcoma (4 papers, 2014 to 2025). An aggressive malignant neoplasm with a poor response to therapy, usually presenting as stage III/IV disease. "A study of genomic profiling of primary histiocytic sarcoma suggests the existence of a distinct subtype of primary histiocytic sarcoma characterized by NF1/PTPN11 alterations with predilection for the gastrointestinal tract." (PMID 39998733, 2025). "Recent studies propose a molecular subclassification of histiocytic sarcoma based on the detection or lack of NF1/PTPN11 mutations." (PMID 40901224, 2025).
infiltrating ductal carcinoma (4 papers, 2014 to 2025). "Tumors induced by Nf1 Indel-editing were predominantly ductal carcinoma in situ (12/13 cases; the remaining two case were a benign papilloma and an invasive ductal carcinoma), all with moderate differentiation and high similarity to one another." (PMID 41000773, 2025).
Kyphoscoliosis (4 papers, 2011 to 2025). An abnormal curvature of the spine in both a coronal (lateral) and sagittal (back-to-front) plane. "Analyses performed on Prss56-Nf1 mutant mice revealed progressive scoliosis, kyphosis, and kyphoscoliosis, closely mirroring the spine deformities observed in patients with NF1." (PMID 41397954, 2025). "Taking the etiology of kyphoscoliosis into consideration, we observed a reduction rate of 0.015 ± 0.010 g/(cm2·month) in 4 (4/6, 67%) NF1, 0.034 ± 0.024 g/(cm2·month) in 5 (5/6, 83%) CS, and 0.029 ± 0.015 g/(cm2·month) in 8 (8/8, 100%) IS cases at LS." (PMID 27896274, 2016).
mismatch repair deficiency (4 papers, 2020 to 2024). "Of note, due to their rarity, a child with a clinical diagnosis of NF1 and HGG should be investigated for constitutional mismatch-repair deficiency (CMMRD) if an NF1 mutation has not been previously identified." (PMID 32582540, 2020).
non-Hodgkin lymphoma (4 papers, 1994 to 2021). Distinct from Hodgkin lymphoma both morphologically and biologically, non-Hodgkin lymphoma (NHL) is characterized by the absence of Reed-Sternberg cells, can occur at any age, and usually presents as a localized or generalized lymphadenopathy associated with fever and weight loss. "While our results are consistent with the recent population-based study in Finland, they are in contrast with the larger population-based study in England whereby NF1 individuals were found to be 3 times more likely to develop both non-Hodgkin lymphoma and lymphocytic leukemia." (PMID 34011343, 2021). "Non-Hodgkin lymphoma was observed in a type-2 deleted patient, but no causality of the NF1 deletion was established." (PMID 34199217, 2021).
pituitary adenoma (4 papers, 2021 to 2026). "Potential associations include variants in emerging pituitary adenoma predisposition genes, including NF1, PRKACB, PAM, and CHEK2." (PMID 41965096, 2026). "One patient with NF1 pathogenic variation (P2) had pituitary adenoma that can cause further subsequent symptoms depending on its hormone production." (PMID 34325699, 2021). "Although pituitary adenomas, PNETs, and PCC have been associated with NF1 gene mutations, the second sister with a PCC did have proven germline CHEK2 with a pathogenic somatic NF1 mutation." (PMID 36440216, 2022). "The PA tissue showed no loss of the wild type allele of the NF1 gene, but harboured a somatic GNAS p.R201C mutation, not supporting NF1 being causative in pituitary adenoma development." (PMID 33805450, 2021).
Pleural effusion (4 papers, 2022 to 2025). The presence of an excessive amount of fluid in the pleural cavity. "This case highlights the importance of considering vascular lesions in NF-1 patients who present with pleural effusion." (PMID 39210188, 2024). "We report the case of an elderly lady with NF-1 who presented with pleural effusion related to the genetic disorder, which was missed, and elaborate on the diagnostic workup done to reach a diagnosis." (PMID 35186543, 2022).
rhabdoid tumor (4 papers, 2020 to 2024). An aggressive malignant embryonal neoplasm usually occurring during childhood. "Known associations included NF1 in LGG and SMARCB1 in atypical teratoid/rhabdoid tumor (AT/RT)." (PMID 36928815, 2023).
spindle cell sarcoma (4 papers, 2020 to 2025). A malignant mesenchymal neoplasm composed of spindle-shaped cells.
stenosis (4 papers, 2021 to 2025). "Patients with NF-1 have altered function of neurofibromin which can cause vascular lesions through arterial stenosis, occlusion, aneurysm formation, and arteriovenous fistulas." (PMID 36127977, 2022). "However, it is possible that the loss of neurofibromin 1 in endothelial cells could be responsible itself for the excessive proliferation of vascular smooth muscle cells leading to arterial stenosis." (PMID 36980803, 2023). "While the loss of NF1 in endothelial cells may contribute to the development of arterial stenosis by altering blood vessel development and function, it is likely that additional factors are involved in the excessive proliferation of vascular smooth muscle cells." (PMID 36980803, 2023). "However, it is not clear whether the loss of NF1 in endothelial cells alone is sufficient to cause the excessive proliferation of vascular smooth muscle cells, which are the cells that contribute to arterial stenosis." (PMID 36980803, 2023).
adenocarcinomas of the stomach (3 papers, 2015 to 2023). "The expression level of NF1 in digestive system tumors, including CHOL (Cholangiocarcinoma), LIHC (Liver hepatocellular carcinoma), PAAD (Pancreatic adenocarcinoma), and STAD (Stomach adenocarcinoma), was found to be higher than that in the adjacent non-cancerous tissue." (PMID 37147639, 2023).
Alzheimer disease (3 papers, 2018 to 2024). A progressive, neurodegenerative disease characterized by loss of function and death of nerve cells in several areas of the brain leading to loss of cognitive function such as memory and language. "Especially the risk for Alzheimer disease was increased among individuals with NF1." (PMID 34257422, 2021). "Diseases—The approaches suggested would change our understanding of a whole range of diseases, such as NF1 (a rare disease involving young adults), neurodegeneration (Parkinson’s, Huntington’s and Alzheimer’s Diseases, and ALS), and cancer." (PMID 38534456, 2024). "Most observations were related to Alzheimer disease (ICD-10 G30), which was observed in 10 individuals with NF1 (HR 2.88, 95% CI 1.47–5.66)." (PMID 34257422, 2021).
arteriopathy (3 papers, 2020 to 2021). "Mutations in the NF1 tumor suppressor gene are linked to arteriopathy." (PMID 34934133, 2021). "Distinguishing the typically self-limiting TCA from the progressive arteriopathy of Moyamoya or NF-1 genetic defects can be problematic, acutely at times, with substantial treatment implications as to which diagnosis is given." (PMID 34122310, 2021). "Here we define the contribution of myeloid subpopulations to NF1 arteriopathy." (PMID 34934133, 2021). "Nf1+/− mutant mice develop a thick neointima, resembling human arterial disease." (PMID 32694667, 2020).
asthma (3 papers, 2006 to 2024). "In this regard, OVA- and HDM-mediated asthma induction reduces optic nerve volumes and proliferation to levels comparable to Nf1+/− mice, thus establishing that asthma blocks optic glioma formation." (PMID 34880260, 2021). "Herein, we establish a mechanistic link between asthma and gliomagenesis by demonstrating that asthma induces decorin expression in T cells to reduce microglia support of Nf1 optic glioma growth." (PMID 34880260, 2021).
Ataxia (3 papers, 2017 to 2025). Ataxia refers to impaired coordination of voluntary muscle movement. "We report a case of a two-year-old boy with a family history of NF1 who presented with headache and ataxia." (PMID 41216086, 2025).
Blindness (3 papers, 2018 to 2025). Blindness is the condition of lacking visual perception defined as a profound reduction in visual perception. "Impaired VA occurred in 55 vs 80% of NF1-associated vs sporadic OPG patients, respectively, while blindness of at least one eye occurred in 36% of individuals." (PMID 40643687, 2025). "However, the degree of the so called partial blindness of NF1+/− fibroblasts varies between different patients." (PMID 29670214, 2018).
Brainstem glioma (3 papers, 2012 to 2023). "In our study, we detected patient #12 diagnosed with a brainstem glioma to have c.3974+1G>A, a splice donor site alteration, disrupting the splicing site at the end of exon 29 of the NF1 gene." (PMID 38139220, 2023). "Brainstem glioma presenting with precocious puberty has been reported in patients with NF-1." (PMID 22970062, 2012).
cholangiocarcinoma (3 papers, 2022 to 2025). A carcinoma that arises from the intrahepatic biliary tree (intrahepatic cholangiocarcinoma) or from the junction, or adjacent to the junction, of the right and left hepatic ducts (hilar cholangiocarcinoma).
conjunctival melanomas (3 papers, 2018 to 2025). "Our study is the first to identify NF1 as a frequently mutated oncogene (33%) in conjunctival melanoma." (PMID 29559732, 2018). "For instance, BRAF V600E and NF1 mutations occur more frequently in conjunctival melanomas." (PMID 39564955, 2024). "In patients with conjunctival melanoma, which involves dysregulation of the MAPK and PI3K/AKT/mTOR pathways, mutations in BRAF, NRAS, and NF1 are commonly observed, while KIT and PTEN mutations occur less frequently." (PMID 41001300, 2025).
Constipation (3 papers, 2017 to 2021). Infrequent or difficult evacuation of feces. "Further studies comprising functional analyses and search for modifier genes may clarify new potential pathogenesis mechanisms associated with constipation in NF1." (PMID 33911094, 2021). "In contrast, constipation-induced groups treated with Dul and a high dose of HLp-nF1 showed similar patterns in the comparative microbiome analysis." (PMID 33872333, 2021). "Further, the number of excreted pellets every week, a representative marker of constipation, was decreased in the constipation-induced group but significantly restored dose-dependently upon treatment with HLp-nF1." (PMID 33872333, 2021). "The intestinal expression of IL-6, IL-1β, TNFα, PGE2, and COX-2 were increased in the constipation-induced group, whereas in the groups treated with HLp-nF1 or Dul, they were significantly decreased." (PMID 33872333, 2021). "In this study, reduced thickness in the intestinal muscularis externa layer was observed in the constipation-induced group, and the administration of HLp-nF1 increased the thickness dose-dependently." (PMID 33872333, 2021). "Similarly, reduced intestinal weight was observed in the constipation-induced group than the HLp-nF1 administration." (PMID 33872333, 2021). "However, the level of serum IL-10 and IL-12 were decreased in the constipation-induced group compared to the control group and were recovered with the administration of HLp-nF1 or Dulcolax (Dul)." (PMID 33872333, 2021). "Moreover, the fecal water content was significantly lower in the constipation-induced group than the control group, whereas in the HLp-nF1-treated groups, it was virtually recovered to the basal level." (PMID 33872333, 2021). "Therefore, the objective of the present study is to investigate the effects of heat-inactivated L. plantarum (HLp-nF1) on loperamide (Lop)-induced constipation in rats by examining changes in their intestinal microbiota, inflammatory substances, and intestinal contractility." (PMID 33872333, 2021). "In this study, both transit length and gastrointestinal motility were decreased in the constipation-induced groups, whereas both were recovered to the near-normal condition with the treatment of >3.2 × 1010 cells/mL HLp-nF1." (PMID 33872333, 2021). "The principal component analysis (PCA) results of the genus analysis revealed that the constipation-induced group was distinctly different from both the pre-preparation (PRE) and control groups, showing a significant change in the genus pattern in the presence of a high dose of HLp-nF1 and Dul." (PMID 33872333, 2021). "Overall, their likelihood of fulfilling the criteria for functional constipation, IBS, or functional dyspepsia was higher with an OR of three compared to their relatives without NF1." (PMID 28814319, 2017).
gastric tumors (3 papers, 2014 to 2020). "This study primarily focused on gastric tumors, and it included a limited number of small intestinal GISTs (6 of 75) as well as rare genotypes (NF1 and BRAF)." (PMID 33048845, 2020).
gynaecomastia (3 papers, 2007 to 2024). "According to this review, the present case appears to be one of the youngest NF1-affected males affected by gynaecomastia that has been reported." (PMID 26668786, 2015).
Headache (3 papers, 2011 to 2021). Cephalgia, or pain sensed in various parts of the head, not confined to the area of distribution of any nerve. "Eighty-one (45%) of these patients were found to have headaches, a frequency that led the study investigators to conclude that patients with NF-1 are at greater risk for headaches than the general population." (PMID 21569290, 2011). "Although headaches are common in patients with NF-1, the frequency has varied between studies." (PMID 21569290, 2011). "Although headaches are very common in patients with NF-1, the specific diagnosis of occipital neuralgia is not." (PMID 21569290, 2011). "This frequency was not statistically significantly different from that found in the general population, leading the study investigators to conclude that headache is not a specific feature of NF-1." (PMID 21569290, 2011).
Hereditary breast cancer (3 papers, 2020 to 2021). Breast carcinoma that has developed in relatives of patients with history of breast carcinoma. "In particular, NF1 alterations have been reported in association with endocrine therapy resistance in lobular breast cancer." (PMID 33059724, 2020).
Huntington disease (3 papers, 2017 to 2023). Huntington disease (HD) is a rare neurodegenerative disorder of the central nervous system characterized by unwanted choreatic movements, behavioral and psychiatric disturbances and dementia. "Dysregulated GABA signaling in the CNS, which causes an increase of GABA-mediated inhibition, has been implicated as a cause of learning defects in mouse models of Huntington’s disease and NF1." (PMID 32074109, 2020). "The neuronal markers that we validated here for GABAergic (GAD67+) and dopaminergic (tyrosine hydroxylase+) neurons, have been used to document imbalanced signaling associated with learning and memory deficits in NF1 and with other cognitive and motor impairments in Huntington’s disease." (PMID 32074109, 2020). "A similar distribution was described in another cohort reporting on PGT for NF1, but also in cohorts describing PGT for Huntington’s disease and monogenic kidney disease." (PMID 37337089, 2023).
leiomyoma (3 papers, 2009 to 2018). A well-circumscribed benign smooth muscle neoplasm characterized by the presence of spindle cells with cigar-shaped nuclei, interlacing fascicles, and a whorled pattern. "In our opinion, the true incidence of uterine leiomyoma associated with NF1 deserves to be explored in a larger series of female patients with NF1, given the previously reported cases of NF1-associated leiomyoma of the gastrointestinal and urinary tracts." (PMID 19946501, 2009). "However, there are several reports suggesting a true link between leiomyoma and NF1." (PMID 19946501, 2009).
Macrocephaly (3 papers, 2013 to 2019). Occipitofrontal (head) circumference greater than 97th centile compared to appropriate, age matched, sex-matched normal standards. "In addition, macrocephaly was observed less frequently than in the cohorts of individuals with the NF1 missense pathogenic variants at residues 844–848 and “classic” NF1 clinical presentation (P = 0.0267 and P = 0.0111, respectively, not statistically significant after B–H correction at FDR 0.05)." (PMID 30190611, 2019).